CCL2 (C-C motif chemokine ligand 2)
Diseases named in the same sentence as CCL2 in open-access papers (continued):
Sharing a sentence is not in itself a finding about the gene and the disease.
tumor (continued). "Chemokines, such as CCL2, which are normally critical for NK migration and tumor elimination, can in fact become immunosuppressive in a tumor microenvironment lacking key NK-activating “costimulatory” cytokines." (PMID 27148255, 2016). "Although CCL2 expression did not affect cell proliferation in vitro, CCL2 overexpression enhanced and CCL2 knockdown suppressed tumor growth, angiogenesis, and macrophage infiltration in vivo." (PMID 27666332, 2016). "Several studies have indicated that modification in the tumor microenvironment by the CCL2 axis also modulates immunological responses." (PMID 27666332, 2016). "Both CCR2 and CCL2 positively correlated with Fuhrman grade (P = 0.004 and P < 0.001, respectively) and presence of tumor necrosis (P < 0.001 and P = 0.021, respectively)." (PMID 27409666, 2016). "Tissue immunostaining showed that six of eight metastatic samples obtained during treatment contained CCL2-positive tumor cells, whereas all samples were stained positive for BRAFV600E and contained the mutated BRAF gene, as shown by sequence analysis." (PMID 26684239, 2016). "The CCL2/CCR2 chemokine axis plays a pivotal role in the migration of MDSCs in cancer, and impairment of CCL2/CCR2 signaling inhibits tumor growth." (PMID 26901500, 2016). "Blockade of CCL2/CCR2 axis in various tumors displayed remarkable therapeutic effects as the versatile functions of macrophages in tumor progression." (PMID 27888616, 2016). "Though this phenomenon is not widely observed in other cancers yet, attention should be aroused when suppressing CCL2/CCR axis is applied for tumor treatment." (PMID 26701209, 2016). "In addition, CCL2/CCR2 signaling could educate tumor-associated macrophages (TAMs) to enhance the production of several kinds of immunosuppressive cytokines and chemokines, which in turn facilitate the progression of tumors and exert an unfavorable effect on cancer patients." (PMID 27409666, 2016). "Both tumor-free and tumor-bearing mice have detectable amounts of CCL2 in serum although tumor-bearing mice have higher levels as their tumors progress after 120 days of age." (PMID 27820834, 2016). "CCL2 expression levels in tumor tissues or surrounding normal tissues were distinguished through flow cytometry staining with antibodies recognizing murine or human specific CCL2." (PMID 27283985, 2016). "Increased T cell tumor infiltration is correlated with increased CCL2 and CCL5 expression in the tumor tissues." (PMID 27014915, 2016). "Apart from direct effects on tumor and endothelial cells, CCL2 also recruits various immune cell subsets including monocytes and macrophages to site of metastasis, and mediates differentiation and polarization of these cell types." (PMID 26885690, 2016). "Chemotherapy promoting chemokine expression in tumor microenvironment affects leukocyte migration, such as CCL2/CCR2 pathway reboots antigen-specific T cell responses." (PMID 26459255, 2016). "In this regard, we have shown that CDDO-Me impedes TAM recruitment to tumors in PyMT mice through inhibition of tumor cell production of CCL2 and CXCL12." (PMID 26918785, 2016). "Numerous studies have found that tumor cell-derived CCL2 promotes macrophage recruitment both in vitro and in vivo." (PMID 26884646, 2016). "One report shows that the treatment of CCL2 with peroxynitrite resulted in an impaired capacity to attract antigen-specific CD8+ T cells into the tumor tissue in mice, whereas CD14+ monocyte chemotaxis remained unaltered." (PMID 27566567, 2016). "Inhibition of CCL2 activity resulted in significant suppression of tumor growth, angiogenesis, and macrophage infiltration." (PMID 27666332, 2016). "Overall, our data indicate that circulating and intratumoral IM are increased in RT-treated tumor-bearing hosts as a result of a radiation specific up-regulation of the monocyte chemokine ligands CCL2 and CCL5." (PMID 27852031, 2016).
tumor (continued). "Chemokine (C-C motif) Ligand 2 (CCL2) was one of such chemokines important for both primary tumor development and metastasis of various cancers." (PMID 27145753, 2016). "To investigate the mechanisms contributing to the decreased growth and invasion of CCL2 deficient tumors, we examined the possibility that reduced bioavailability of CCL2 protein would inhibit stromal reactivity in the primary tumor." (PMID 27283985, 2016). "Endothelial cells, macrophages, smooth muscle cells, fibroblasts, and even tumor cells can produce CCL2." (PMID 27271610, 2016). "Immunostaining revealed that tumor cells were the main cellular source of CCL2, whereas a minor amount of staining was due to immune infiltrate (not shown)." (PMID 26684239, 2016). "The expression levels of CCL2 in peritumoral tissue and tumor tissue were statistically significant (r = 0.429, p < 0.05)." (PMID 27271610, 2016). "During the course of this study, we also analysed serums from the tumor bearing animals and assessed CCL2 levels." (PMID 27097645, 2016). "With infusion of in vitro-generated Th17 cells, lungs of mice bearing B16 melanoma tumors had elevated dendritic cell and activated T cell recruitment, as well as elevated CCL20 and CCL2 expression, chemokines known to recruit these anti-tumor immune cells." (PMID 27784305, 2016). "In a genetic mouse model of CRC, inactivation of Ccl2 caused depletion of CCR2+ TAM at the tumor site and reciprocal accumulation of CTL, which prevented tumor progression." (PMID 27136535, 2016). "It is important to point out, however, that CCL2 inhibition using the CNTO888 antibody has shown robust anti-tumor responses in several pre-clinical cancer models." (PMID 26885690, 2016). "A possible mediator of IDO1-dependent Treg expansion is the increase of chemokines like CCL2 which attracts Treg cells, leading to a global tumor immune tolerance." (PMID 27174915, 2016). "In our studies, we demonstrated that CCL2 gene silencing in MDA-MB-231 tumor xenografts inhibited ALDH1 expression, and reduced the number of CD24-/CD44+ cells." (PMID 27283985, 2016). "Previous studies have mainly used neutralizing antibodies to evaluate the role of CCL2 in tumor progression." (PMID 27283985, 2016). "The expression of Cxcl12 and Ccl2 was also measured in the tumor microenvironment, and data show the expression of Cxcl12 and Ccl2 to be increased in the HSC co-transplantation group." (PMID 26758420, 2016). "Silencing of CCL2 in tumor tissues down-regulated CCL2 protein expression to levels found in normal mammary tissues." (PMID 27283985, 2016). "Specifically, although tumors in CCL2-deficient mice have the same total number of TAMs as tumors in wild type mice, Ccl2 disruption is associated with a profound reduction in the numbers of endothelial precursor cells (EPCs) in the bone marrow and circulation which may suppress tumor angiogenesis." (PMID 27820834, 2016). "CCL2 acting via its receptor C-C chemokine receptor 2 (CCR2) is a direct mediator of monocyte recruitment to the primary tumor and to metastases in the Polyoma Middle T oncoprotein (PyMT) model." (PMID 27191744, 2016). "Among the cytokines expressed in the tumor microenvironment and in the circulation in cancer patients, the chemokine monocyte chemoattractant protein-1 (CCL2) has been detected in most types of solid cancers." (PMID 26684239, 2016). "Compared to Ca-TAT/control siRNA treatment, Ca-TAT delivery of either CCL2 siRNAs reduced HMGB1 in the primary tumor by over 75%, further demonstrating increased necrosis in the primary tumor with CCL2 gene silencing." (PMID 27283985, 2016). "Serum levels of CCL3 were positively related to the tumor size, while the CCL2/CCL3 ratio in OSCC patients was correlated to TNM (tumor, node, metastasis)." (PMID 27044404, 2016). "CCL2 acts as a classical chemokine that can effectively attract and activate monocytes/macrophages to local tissue damage, inflammation, tumor, and other sites." (PMID 27271610, 2016).
tumor (continued). "The affinity between chemokine (C-C motif) ligand 2 (CCL2) released by tumor cells and chemokine (C-C motif) receptor 4 (CCR4) expressed on Treg cells has been shown to play a major role in the recruitment of Treg cells to tumor sites." (PMID 27887569, 2016). "We determined that CCL2 transcript levels in irradiated tumors were increased up to ten fold when compared to unirradiated tumor controls 2, 3, and 4 days post-RT." (PMID 27852031, 2016). "CDDO-Me also inhibited expression of chemokines that mediate selective recruitment of TAMs and M2 macrophages, (CCL3, CCL4, and eotaxin) and monocytic infiltration of tumor sites (CCL2 and CCL5)." (PMID 26918785, 2016). "CCL2 can be produced by both cancer and stromal cells in the tumor microenvironment, exerting direct effects on cancer cells and functioning indirectly by recruiting host stromal cells with pro-tumorigenic activities during metastasis." (PMID 26885690, 2016). "We next explored the roles of CCL2 in regulating tumor growth in vivo using nude mouse xenograft models." (PMID 27666332, 2016). "CCL2 also plays a crucial role in the recruitment of inflammatory macrophages to the tumor site and become TAMs that are suggested to enhance tumor malignancy." (PMID 27541266, 2016). "We also show that dl922-947-mediated reduction of the monocyte-attracting chemokine CCL2 decreased monocyte chemotaxis in vitro and tumor macrophage density in vivo." (PMID 26625205, 2016). "Suppressed miR-126/126* levels lead to an increased levels of both SDF-1α and CCL2 thereby promoting tumor cell proliferation and recruitment of MSCs and inflammatory monocytes in the TME." (PMID 27231010, 2016). "Apart from recruiting and educating TAMs, CCL2/CCR2 has been reported to be responsible for the accumulation of myeloid-derived suppressor cells (MDSCs) in tumor sites." (PMID 27409666, 2016). "Serum CCL2 and CCL2/CCR2 expression level were remarkably increased in NPC patients compared to non-tumor patients by ELISA and IHC analyses." (PMID 26701209, 2016). "We found that the combination of anti-VEGFA and anti-CCL2 yielded better suppression efficiency on tumor growth, angiogenesis, TAMs accumulation, and lung metastasis than either single antibody application." (PMID 27541266, 2016). "Stimulation of CAFs and MSCs with tumor cell-derived conditioned media leads to upregulation of various chemokines, including CCL2, CXCL8, and CCL5." (PMID 26884646, 2016). "TAMs are macrophages, derived predominantly from bone marrow monocytes, which are recruited by TME-derived CCL2 to infiltrate tumor tissues." (PMID 27231010, 2016). "In contrast, other studies reported that introduction of the CCL2 gene into tumor cells correlated with decreased tumorigenicity and facilitated immune mediated tumor rejection." (PMID 27564257, 2016). "The CCL2/CCR2 signaling axis has recently been implicated in tumor development, suggesting endothelial expression of CCR2 to increase vascular permeability and responsiveness to CCL2 positive monocyte infiltration." (PMID 25909848, 2015). "Accordingly, the results suggest that the CCL2 immunomodulation is leveraged from tumor cells to macrophages with increasing PDT-induced tumor cell death." (PMID 26307977, 2015). "As an example, tumor-promoting macrophages are recruited to tumor cells by chemotactic factors including CCL2, VEGFA, and M-CSF." (PMID 26000250, 2015). "This study emphasises the tumour microenvironment as the critical determinant of successful anti-metastatic therapy, heeding that extreme caution be exercised when considering anti-CCL2 treatment in metastatic disease." (PMID 25990313, 2015). "Numerous cancers express tumor-derived factors, such as CSF-1 and CCL2, to recruit monocytes and promote their differentiation to macrophages in the tumor microenvironment." (PMID 26231039, 2015).
tumor (continued). "Cells in the tumor microenvironment, including both tumor cells and stromal cells, overexpressed chemokines such as CCL2 (MCP-1), CXCL12 (SDF-1), CCL9 (MIP-1γ) and/or CCL18 (PARC), and recruit MOs into the tumor bed." (PMID 26155942, 2015). "As an inflammatory medium, CCL2 is the predominant chemotactic protein, which attracts macrophages into the tumor environment from the blood." (PMID 25695619, 2015). "Whereas the intensity of CCL2 immune signaling by tumor cells was proportionally reduced by photo-oxidative damage, the CCL2 signaling by macrophages was inversely proportional to tumor cell viability." (PMID 26307977, 2015). "Cathepsins S (CatS) has been implicated in numerous tumourigenic processes and here we document for the first time its involvement in CCL2 regulation within the tumour microenvironment." (PMID 26358505, 2015). "These tumor cells release abundant amounts of chemokine CCL2 which attracts monocytes that within the tumor stroma develop into M2 macrophages." (PMID 26593954, 2015). "Overall, the levels of the inflammatory markers evaluated (NAG, TNF-α, CCL2) in the implant-bearing tumors were also influenced by the inflammation phase in which the tumor cells were grown." (PMID 26158775, 2015). "This suggests that the sMSC-derived ANGPT2 and CCL2 play a key role in the sMSC-induced tumor growth." (PMID 25883937, 2015). "CCL2, a contributing factor for M2 macrophage polarization, is a chemokine also known for its role in both tumor growth and myeloid cell modulation." (PMID 26459393, 2015). "Ccl2 and Ccl5 have been reported to be involved in the mobilization and homing of MCs to tumor sites and to participate in the maintenance of a proinflammatory state that favors tumor growth as well as metastatic colonization." (PMID 26218064, 2015). "That is, once metastatic seeding has occurred, the role of CCL2 in monocyte differentiation and tumor cell migration is diminished." (PMID 26327448, 2015). "Another cytokine, chemokine, CCL2, is responsible for recruiting inflammatory monocytes to the tumor site." (PMID 26158775, 2015). "Positive; coinoculation of athymice nude mice with PC3+U937IL-4 or PC3+U937 decreased time to critical tumor mass and increased angiogenesis and CCL2 expression compared to PC3 alone." (PMID 26217583, 2015). "In the breast cancer model, the tumor cells produced CCL2 that induced neutrophil ROS production, while, in the renal carcinoma model, tumor-derived IL-8 recruited tumor cytotoxic neutrophils." (PMID 26819959, 2015). "In general, tumor cells and stroma overexpress CCL2, which results in increased MO recruitment and TAM generation." (PMID 26155942, 2015). "Interrogation of tumours and serum revealed genetic ablation of CatS leads to the depletion of several pro-inflammatory chemokines, most notably, CCL2." (PMID 26358505, 2015). "The tumour microenvironment is highly complex and we have shown dual roles for the cytokine, CSF-1 and CCL2 in the context of macrophage activation, suggesting a spectrum of macrophage activation states." (PMID 26174804, 2015). "Conversely, systemic levels of CCL2 were higher in animals bearing tumor alone than those in which the tumor cells grew intra-implant." (PMID 26158775, 2015). "For example, CCL2 secreted from both tumour and stromal cells was reported to mediate interaction between inflammatory monocytes and tumour cells." (PMID 26465273, 2015). "This would help explain the fact that tumor cells up-regulate CCL2 to attract monocyte infiltration into GBM, while on the other hand they do not express CX3CL1." (PMID 25987130, 2015). "CCL8 and CCL2 secreted by tumor cells were reported to recruit monocytic cells, and CXCL1 and MIF were linked to the recruitment of MDSCs." (PMID 25514599, 2015). "In concordance with this, Celastrol, a novel p536 inhibitor, can also significantly inhibit VCaP tumor growth in vivo and target CCL2 expression." (PMID 25749044, 2015).
tumor (continued). "One promising intervention is neutralisation of macrophage attractant C-C chemokine ligand 2 (CCL2), which is thought to target monocyte migration into the tumour microenvironment." (PMID 25990313, 2015). "TNF was most potent in myofibroblast cultures, suggesting ADT induces CCL2 via paracrine interactions within the tumor microenvironment." (PMID 26327448, 2015). "In contrast to the IL-17 antitumor activity observed in mice injected with splenocytes, we observed that IFN-gamma, IL-6, IL-23, Ccl2, and Ccl20 proteins were significantly increased in tumor tissues of mice injected with IL-17." (PMID 26684834, 2015). "Next, we intravenously inoculated 5TGM1 cells into the mice and treated them with either control IgG or neutralizing antibodies against CCL3 or CCL2 (100 μg per mouse each time, intraperitoneally injected 1 day before and 7 days after tumor cell inoculation)." (PMID 26155942, 2015). "Another important player in post-PDT immunity is CCL2, the main function of which is to promote immune cell chemoattraction to the damage site and hence mediate the anti-tumor immune response after treatment." (PMID 26307977, 2015). "Macrophages were exposed to the adipocyte and tumor paracrine factors leptin, CCL2 and lauric acid (alone or in combinations)." (PMID 25599228, 2015). "IL1β activated the p38 MAPK signaling pathway and expression of monocyte chemoattractant protein (MCP-1/CCL2) by tumor cells." (PMID 25987130, 2015). "Together with CCL2 chemokine, IL-6 is the pro-inflammatory and tumor-promoting cytokine that we have seen consistently upregulated in our tumor model by the different cell types examined or their crosstalk." (PMID 25599228, 2015). "In this model, anti-CCL2 antibody treatment also inhibited the migration of adoptively transferred inflammatory monocytes (IMs; CD11b+Ly6Chigh) to the tumor challenged lung." (PMID 26275794, 2015). "Taken together, this data would suggest that CatS can control CCL2 expression within different tumour cell types and that proteolytic activity of the protease is important in mediating this effect." (PMID 26358505, 2015). "We confirmed the paracrine mechanism by employing mixed cultures of tumor and microenvironment cells and, analogously, by measuring in vitro metastatic phenotypes (migration and invasion) that depend on CCL2 signaling." (PMID 26327448, 2015). "To further confirm the correlation of Ser536 phosphorylation with CCL2 expression, we also accessed their expression levels in VCaP xenograft tumor samples we collected previously." (PMID 25749044, 2015). "Expression of both CSF-1 and CCL2 have been independently correlated with cancer progression in several tumour types." (PMID 26174804, 2015). "Analysis was performed using a range of human tumour types (colorectal, breast and brain carcinomas) and a significant correlation between CatS and CCL2 expression was observed in all tumour datasets examined." (PMID 26358505, 2015). "The chemokine MCP-1/CCL2 is involved in multiple stages of tumor progression, such as recruitment of immunosuppressive, tumor-promoting M2 macrophages, angiogenesis, tumor invasion, and metastasis." (PMID 26167165, 2015). "For example, tumor-associated NK cells are shown to downregulate activating receptors and become less cytotoxic and downregulation of essential chemokines like CCL2 can prevent NK cell trafficking to the site of a developing tumor." (PMID 26161419, 2015). "Conversely, the levels of CCL2 chemokine were lower in implant-bearing tumors from both groups, as compared with those from tumor alone." (PMID 26158775, 2015). "TAMs originate from circulating monocyte precursors that are recruited to the tumor by tumor-derived signals, including chemokine (C-C motif) ligand 2 (CCL2) and macrophage colony-stimulating factor (M-CSF)." (PMID 26021873, 2015).